ANGPTL4 (angiopoietin like 4)
Diseases named in the same sentence as ANGPTL4 in open-access papers (continued):
Sharing a sentence is not in itself a finding about the gene and the disease.
diabetic eye disease (3 papers, 2017 to 2022). A group of disorders affecting the eye in patients with diabetes mellitus. "They demonstrated that hypoxia induces ANGPTL4 in retinal Müller glial cells, furthermore, in the retina of ischemic retinal disease models and in eyes of patients with diabetic eye disease, the expression of ANGPTL4 is considerably high." (PMID 30049845, 2018).
E. coli infection (3 papers, 2019 to 2024). "While the sequencing identified a total of 408 DEGs in the cells upon ANGPTL4 treatment, we focused on two significantly enriched pathways involving “pathogenic E. coli infection” and “leukocyte transendothelial migration”." (PMID 31766605, 2019). "Our recent study has demonstrated that Angptl4 was markedly elevated in meningitic E. coli infection of hBMECs as well as in a mice model, and the induction of Angptl4 contributes to BBB disruption via ARHGAP5/RhoA/MYL5 signaling cascade." (PMID 36769171, 2023). "Therefore, we hypothesized that VEGFA, PDGFB, and ANGPTL4 may be the potential target genes of Egr-1 in meningitic E. coli infection of hBMEC." (PMID 38233877, 2024). "Our previous RNA-sequencing work have found that the ANGPTL4 gene was significantly upregulated (p ≤ 0.05) in human BMECs (hBMECs) in response to meningitic E. coli infection, speculating a potential role of this gene during meningitic E. coli invading the BBB." (PMID 31766605, 2019). "Meningitic E. coli infection can induce VEGFA, PDGFB, and ANGPTL4 expression, aggravating infection-dependent BBB dysfunction." (PMID 38233877, 2024).
giant cell tumor (3 papers, 2017 to 2019). A benign, intermediate, or malignant tumor that arises from the bone or soft tissue. "Although ANGPTL4 is over-expressed in a range of epithelial tumours there is only one other report in primary bone tumours, where it was recently shown that ANGPTL4 is over-expressed in Giant Cell Tumour of Bone." (PMID 29739381, 2018). "Although emerging studies have implicated that Aiopoietin-like 4 Protein (ANGPTL4) is related to the aggressiveness and metastasis of many tumors, the role of ANGPLT4 in giant cell tumor (GCT) of bone was rarely investigated." (PMID 28903395, 2017). "Similarly, the stimulatory effect of conditioned media collected from Giant Cell Tumour of Bone stromal cells on osteoclast formation was inhibited in ANGPTL4 knock-out cells." (PMID 29739381, 2018).
Granuloma (3 papers, 2021 to 2022). A compact, organized collection of mature mononuclear phagocytes, which may be but is not necessarily accompanied by accessory features such as necrosis. "In conclusion, the granuloma, the caseous necrosis, the epithelioid reaction, the microangiosis, the fibrous connective tissue, ANGPTL-4, and MMP-9 may become new supporting evidence to identify BS and TS patients." (PMID 33959835, 2021). "Another research has found that the ANGPTL4 knockout mice fed with high-fat diet show granuloma lesions in the intestine and WAT, as well as lymphangitis and mesenteric lymphadenitis, which suggests that ANGPTL4 is essential to the lymphatic drainage of lipids from WAT to the liver." (PMID 33593372, 2021).
Hyperglycemia (3 papers, 2018 to 2025). An increased concentration of glucose in the blood. "The association between the presence of hyperglycaemia in the mother and altered cord blood levels of leptin, adiponectin, and ANGPTL4 has been identified in previous studies." (PMID 29861725, 2018). "In addition, other factors besides intrauterine hyperglycaemia may affect the activity of a number of genes, including ANGPTL4, in the fetus." (PMID 29861725, 2018). "However, we could not prove the causal relationship between intrauterine hyperglycaemia and the expression of the ANGPTL4 gene, given the absence of differences between the level of expression of ANGPTL4 in groups with different glycaemic targets." (PMID 29861725, 2018). "Maybe, the reduced level of activity of ANGPTL4 contributes to the development of GDM in the mothers, that is, it is the cause, not the consequence of hyperglycaemia." (PMID 29861725, 2018).
Kaposi's sarcoma (3 papers, 2016 to 2025). A malignant neoplasm characterized by a vascular proliferation which usually contains blunt endothelial cells. "Although initially considered to be anti-angiogenic, subsequent work has demonstrated that ANGPTL4 promotes the angiogenic and exudative phenotypes that are characteristic of the unique vascular tumor, Kaposi's sarcoma." (PMID 26761211, 2016). "In this regard, many in vitro and in vivo experiments have confirmed dramatic elevation of ANGPTL4 in endothelial cells to express a deregulated herpesvirus-8 (HHV-8)-encoded G protein-coupled receptor (GPCR), which is considered a key factor in Kaposi’s sarcoma tumorigenesis." (PMID 33726754, 2021).
malaria (3 papers, 2021 to 2025). Malaria is a serious and sometimes fatal disease caused by a parasite that commonly infects a certain type of mosquito which feeds on humans. "Two other biomarkers, Angiopoietin-like-4 and Inhibin-βE were able to differentiate children with cerebral malaria within the severe malaria group, showing increased sensitivity after combination in a biomarker signature." (PMID 37788095, 2023). "CXCL10, like VEGF and ANGPTL4, is present in significantly higher concentrations in culture supernatants of ECs stimulated with plasma from malaria patients compared to plasma from healthy individuals." (PMID 34359826, 2021). "Significantly lower amounts of ANGPTL4 can be detected in the plasma of malaria patients compared to the plasma of healthy individuals." (PMID 34359826, 2021). "On average, there was less ANGPTL4 in the plasmas of the malaria patients than in the plasmas of the controls (HAll: 656.8 ± 1108.7 ng/mL, MAll: 149.9 ± 93.4 ng/mL); however, this was not significant." (PMID 34359826, 2021). "Stimulation with plasma from malaria patients resulted in an increase in the measured amount of ANGPTL4 in comparison to the controls (HAll: 13.8 ± 3.4 ng/mL, MAll: 16.4 ± 5.6 ng/mL, p = 0.0691)." (PMID 34359826, 2021). "Our studies showed that co-incubation of brain ECs with plasma from malaria patients resulted in significantly increased secretion of IL-11, CXCL5, CXCL10, VEGF and angiopoietin-like protein 4 (ANGPTL4)." (PMID 34359826, 2021). "Culturing ECs with plasma from malaria patients (27 returning travellers) resulted in significantly increased secretion of IL-11, CXCL5, CXCL8, CXCL10, vascular endothelial growth factor (VEGF) and angiopoietin-like protein 4 (ANGPTL4) if compared to matching controls (22 healthy individuals)." (PMID 34359826, 2021). "The biological function of the 3 candidate biomarkers, ADAMTS18, ANGPTL4, and INHBE, has not been extensively characterized, and they have not been described before in the context of malaria." (PMID 37788095, 2023). "An inverted ratio in cytokine concentration between the malaria and control group in plasma and supernatant, as observed in CXCL5 and ANGPTL4, does not constitute a contradiction." (PMID 34359826, 2021).
myeloma (3 papers, 2017 to 2024). "SERPINE1 (together with ANGPTL4, GDF15, CXCL12, SOX9, HOXB6, and ANK3) was even described as a TA-MSC factor, namely, in mesenchymal stromal cells of the bone marrow that supported myeloma cell growth." (PMID 39011489, 2024). "One of the most upregulated genes in MSCs after myeloma contact was angiopoietin-like 4 (ANGPTL4), which mediates multiple roles in myeloma cell attachment, angiogenesis, regulation of lipid metabolism, and OC resorption." (PMID 34067236, 2021). "Contact of multiple myeloma cells with mesenchymal stem cells or pre-osteoblasts increased expression of ANGPTL4 in the non-malignant population and enhanced myeloma cell adhesion." (PMID 28458654, 2017).
ovarian tumor (3 papers, 2015 to 2021). "Taken together, our data suggest that specifically suppressing ANGPTL4 in ovarian tumors decreases vascular angiogenesis through dissociation of the VEGFR2/VE-cadherin/Src complex and phosphorylation of VEGFR2 at Y949 and therefore inhibits tumor growth and metastasis." (PMID 33726754, 2021). "The expression levels of ANGPTL4, PYGB and IRS2 were upregulated and those of ISG20 and SEH1L were downregulated in ovarian tumor tissues compared with normal tissues." (PMID 34229669, 2021). "Immunoprecipitation analysis showed that suppression of ANGPTL4 was accompanied by dissociation of the VEGFR2/VE-cadherin/Src complex and phosphorylation of VEGFR2 Y949 in A2780 and CAOV3 ovarian tumors." (PMID 33726754, 2021). "Consistent with other studies, we observed that ANGPTL4, PYGB and IRS2 were highly expressed in ovarian tumor tissues and patients with high expression of ANGPTL4, PYGB or IRS2 had significantly lower OS rates than patients with low expression of these factors." (PMID 34229669, 2021). "We chose ANGPTL4 and HER3 to follow up in a cohort of ovarian tumour samples." (PMID 26205780, 2015).
papillary thyroid cancer (3 papers, 2021 to 2023). "ANGPTL4 has been identified as an oncogene in papillary thyroid carcinoma (PTC)." (PMID 35581376, 2022).
prediabetes (3 papers, 2019 to 2025). "We, therefore, investigated the effect of short-term cooling on plasma ANGPTL3 and ANGPTL8, in comparison with ANGPTL4, in relation to changes in lipid metabolism in young, healthy, lean men as well as middle-aged men with overweight and prediabetes." (PMID 31416197, 2019). "In middle-aged men with overweight and prediabetes, short-term cooling also increased ANGPTL4 levels (193 ± 27 vs. 234 ± 31 ng/mL, +15%, p < 0.001)." (PMID 31416197, 2019). "First, we show that short-term cooling increased plasma ANGPTL4 levels in both young, healthy, lean men and middle-aged men with overweight and prediabetes." (PMID 31416197, 2019). "Here, we confirmed that short-term cooling increases plasma ANGPTL4 levels in both young, healthy, lean men and middle-aged men with overweight and prediabetes." (PMID 31416197, 2019). "In middle-aged men with overweight and prediabetes, short-term cooling only significantly increased plasma ANGPTL4 levels (+15%, p < 0.05), but not ANGPTL3 (230 ± 9 vs. 251 ± 13 ng/mL, p = 0.051) or ANGPTL8 (2.2 ± 0.5 vs. 2.3 ± 0.5 μg/mL, p = 0.46)." (PMID 31416197, 2019).
proliferative diabetic retinopathy (3 papers, 2017 to 2025). Advanced retinopathy due to diabetes mellitus characterized by the formation of new vessels in the retina. "ANGPTL-4 was identified in areas of retina neovascularization, and its levels are increased in eyes with proliferative diabetic retinopathy." (PMID 28835854, 2017). "Elevated levels of ANGPTL2, ANGPTL4, and ANGPTL8 have been detected in the vitreous humor of patients with proliferative diabetic retinopathy (PDR), while serum ANGPTL3 levels have been found to correlate positively with DR severity." (PMID 40559376, 2025). "In the test of proliferative diabetic retinopathy (PDR) patients, it was found that the levels of ANGPTL-4 in the vitreous and serum of PDR patients were higher than those in the control group, and the expression level of VEGF was positively correlated with ANGPTL-4." (PMID 35004861, 2021).
pulmonary fibrosis (3 papers, 2021 to 2024). Chronic progressive interstitial lung disorder characterized by the replacement of the lung tissue by connective tissue, leading to progressive dyspnea, respiratory failure, or right heart failure. "Additionally, they used a recombinant ANGPTL4 intervention, which made the progression of pulmonary fibrosis much worse." (PMID 38992710, 2024). "ANGPTL4 (an angiopoietin-like protein belonging to a superfamily of secreted proteins) is involved in angiogenesis, which could be related to the development of pulmonary fibrosis." (PMID 34983465, 2022).
rectal cancer (3 papers, 2022 to 2025). A primary or metastatic malignant neoplasm that affects the rectum. "We found limited evidence to support differences in the association of ANGPTL4 with colon and rectal cancer risk in genetic studies though these analyses were likely underpowered to detect heterogeneity." (PMID 40511612, 2025). "In this study, ANGPTL4 was significantly overexpressed in neutrophils and was associated with a poor prognosis of rectal cancer." (PMID 35548187, 2022).
systemic lupus erythematosus (3 papers, 2022 to 2024). An autoimmune multi-organ disease typically associated with vasculopathy and autoantibody production. "Urinary L-selectin and Angptl4 preceded or coincided with worsening renal disease activity as measured by the renal domains of the Systemic Lupus Erythematosus Disease Activity Index (rSLEDAI), supporting a causal relationship between their elevation and LN severity." (PMID 38673612, 2024). "In addition, we also found that FNLS-YE1 could efficiently introduce protective alleles in TYK2 /WDFY4 and PCSK9/ANGPTL4, offering a potential approach to reduce susceptivity for systemic lupus erythematosus (SLE) and familial hypercholesterolemia (FH), respectively." (PMID 37285261, 2023). "Other promising urine biomarkers—such as Angptl4, L-selectin, TPP1, and TGFβ1—also had high ROC AUC values for distinguishing patients with lupus and AR from those with iSLE, with the combination of Angptl4, L-selectin, and TPP1 yielding the highest discrimination with an AUC of 0.97." (PMID 38673612, 2024).
urothelial carcinoma (3 papers, 2018 to 2023). A malignant neoplasm derived from the transitional epithelium of the urinary tract (urinary bladder, ureter, urethra, or renal pelvis). "In urothelial carcinoma, ANGPTL4 exerted both oncogenic and tumor-suppressive roles, furthermore, circulating ANGPTL4 level was a biomarker of tumor progression." (PMID 30049845, 2018). "In addition, some studies have also showed that ANGPTL4 had tumor-suppressive role, even dual roles in some cancers such as urothelial carcinoma." (PMID 37938151, 2023).
acute kidney injury (2 papers, 2024). Sudden and sustained deterioration of the kidney function characterized by decreased glomerular filtration rate, increased serum creatinine or oliguria. "Additionally, in a cisplatin-induced acute kidney injury mouse model, increased ANGPTL4 expression was observed alongside reduced LPL activity, predominantly in the proximal tubular segments, suggesting that ANGPTL4 may be involved in the AKI mechanism by regulating LPL activity." (PMID 39840089, 2024).
acute pancreatitis (2 papers, 2020 to 2022). An acute inflammatory process that leads to necrosis of the pancreatic parenchyma. "This prompted us to investigate the precise role of ANGPTL4 during acute pancreatitis‐induced tissue injury and subsequent local and systemic inflammation." (PMID 32638512, 2020). "Our microarray analysis of pancreatic tissues from mild and severe acute pancreatitis mice models identified angiopoietin‐like 4 (ANGPTL4) as one of the most significantly upregulated genes." (PMID 32638512, 2020). "ANGPTL4 was continuously expressed during acute pancreatitis, in both the AP to SAP models." (PMID 32638512, 2020). "Overall, ANGPTL4 and C5a might be therapeutic targets for acute pancreatitis and antibodies that target ANGPTL4 or C5a could be effective in treating this disease." (PMID 32638512, 2020).
atrial fibrillation (2 papers, 2021 to 2023). A disorder characterized by an electrocardiographic finding of a supraventricular arrhythmia characterized by the replacement of consistent P waves by rapid oscillations or fibrillatory waves that vary in size, shape and timing and are accompanied by an irregular ventricular response. "The present study’s objective was to investigate the association between angiopoietin-like 4 (ANGPTL4) levels and the prognosis of Atrial fibrillation (AF), the causative effect in angiotensin II- (Ang II) induced AF, and its underlying mechanisms." (PMID 37051105, 2023). "The study speculates the hypothesis that ANGPTL4 is a protective factor of atrial fibrillation, as evidenced by reduced expression of ANGPTL4 in Ang-II-infused mice and suppressive effect of ANGPTL4 on abnormal atrial electrogram changes in mice with Ang II infusion." (PMID 34422410, 2021).
bone cancer (2 papers, 2018 to 2021). A primary or metastatic malignant neoplasm affecting the bone or articular cartilage. "ANGPTL-4 has already been shown to be up-regulated by TGF-β in breast and bone cancer, but the relationship between ANGPTL-3 and TGF-β is not so clear." (PMID 34360721, 2021).
Cachexia (2 papers, 2015 to 2019). Severe weight loss, wasting of muscle, loss of appetite, and general debility related to a chronic disease. "The increase in ANGPTL-4 levels in plasma and tumor tissue in cancer cachexia patients was also positively correlated and associated to the levels of proinflammatory factors in the tumor and mesenteric adipose tissues." (PMID 31741709, 2019). "Our results suggest an opposite effect of ANGPTL-4 depending on the concentration and presence of cachexia." (PMID 31741709, 2019). "Contrary to these observations, we found an increase in the concentration of ANGPTL-4 only in cancer-cachexia patients as compared to the other two groups." (PMID 31741709, 2019). "Taken together, it is reasonable to suggest that ANGPTL-4 secretion in cancer depends on the type of tumor cell and may be related to the development of cachexia, depending of tissues levels and plasma concentration." (PMID 31741709, 2019). "This led us to believe that the proinflammatory condition combined with decreased food consumption and anorexia, which may be present in patients with cancer cachexia, may be responsible for the increased levels of ANGPTL-4 in these patients as compared to the stable weight and control groups." (PMID 31741709, 2019). "Therefore in weight stable patient the ANGPTL-4 levels were lower in plasma and tumor in comparison to CC group, and increased ANGPTL-4 levels may contribute for a proinflammatory environment on cancer cachexia patients." (PMID 31741709, 2019). "Similarly, these results suggest that the increase in ANGPTL-4 and decrease in FADD in the tumor may be associated to advance of cachexia in cancer patients." (PMID 31741709, 2019).
Cerebral ischemia (2 papers, 2022 to 2023). Restriction of arterial blood supply to the brain associated with insufficient oxygenation to support the metabolic requirements of the tissue. "Angptl4 can suppress the upregulation of VEGF in the vascular endothelium after stroke and relieve the increase in BBB permeability caused by cerebral ischemia and thrombolytic therapy." (PMID 35656098, 2022). "In addition, Angptl4 showed a neuroprotective effect in the treatment of cerebral ischemia." (PMID 37533068, 2023). "Ang1, Angptl4 and erythropoietin can protect the BBB after cerebral ischemia, whereas Ang2 and VEGF damage the BBB." (PMID 35656098, 2022).
chronic hepatitis B (2 papers, 2013 to 2014). "One study has demonstrated that serum ANGPTL4 protein in HCC patients is higher than in chronic hepatitis B patients and normal controls." (PMID 25148701, 2014). "Previous studies have also shown that serum ANGPTL4 was significantly increased in HCC patients, compared with chronic hepatitis B patients and normal controls, and ANGPTL4 levels were significantly higher in HCC patients with intrahepatic metastasis and macrovascular invasion than those without." (PMID 23925665, 2013).
colitis (2 papers, 2017 to 2023). Inflammation of the colon. "The exogenous angiopoietin-like 4 protein can mitigate DSS-induced colitis through reducing CD8+ T cells in the colon." (PMID 37693835, 2023).